HOPX (HOP homeobox)
Description:
Atypical homeodomain protein which does not bind DNA and is required to modulate cardiac growth and development. Acts via its interaction with SRF, thereby modulating the expression of SRF-dependent cardiac-specific genes and cardiac development. Prevents SRF-dependent transcription either by inhibiting SRF binding to DNA or by recruiting histone deacetylase (HDAC) proteins that prevent transcription by SRF. Overexpression causes cardiac hypertrophy (By similarity). May act as a tumor suppressor. Acts as a co-chaperone for HSPA1A and HSPA1B chaperone proteins and assists in chaperone-mediated protein refolding.
Synonyms: HOD; HOP; LAGY; NECC1; OB1; SMAP31; CAMEO; TOTO
Tractability: No criterion of Open Targets' tractability assessment is met for any kind of drug.
Gene: Protein-coding gene on chromosome 4 (56,647,989 to 56,681,877, reverse strand). Ensembl gene ENSG00000171476.
Subcellular location: Nucleus; Cytoplasm
Subcellular location (Human Protein Atlas): Nuclear bodies; Cytosol
Pathways (Reactome):
Developmental Biology: Differentiation of Keratinocytes in Interfollicular Epidermis in Mammalian Skin
Gene Ontology:
Molecular function: protein binding; DNA binding
Biological process: chaperone-mediated protein complex assembly; negative regulation of cell differentiation; trophectodermal cell differentiation; bundle of His development; regulation of transcription by RNA polymerase II; cell differentiation
Cellular component: nucleus; chromatin; cytoplasm
Genetic constraint (gnomAD): Loss-of-function variants: 3 observed, 5.52 expected, observed/expected ratio (o/e) 0.54, 90% interval 0.25 to 1.38. That is too few expected variants to judge how well the gene tolerates losing a copy. Missense variants: 84 observed, 76.23 expected, observed/expected ratio (o/e) 1.1, 90% interval 0.92 to 1.32. Synonymous variants: 32 observed, 34.02 expected, observed/expected ratio (o/e) 0.94, 90% interval 0.71 to 1.26.
Homologues: Orthologues: pig HOPX (84% identical), dog HOPX (80% identical), rabbit HOPX (76% identical), guinea pig HOPX (74% identical), mouse Hopx (74% identical), rat Hopx (74% identical), chimpanzee HOPX (71% identical), macaque HOPX (69% identical), tropical clawed frog hopx (51% identical), zebrafish hopx (49% identical), Caenorhabditis elegans ceh-89 (24% identical).
Diseases named in the same sentence as HOPX in open-access papers:
HOPX is named in the same sentence as 71 diseases in open-access papers, as found by Europe PMC text mining. Sharing a sentence is not in itself a finding about the gene and the disease. The quoted sentences say what the papers report.
lung carcinoma (14 papers, 2004 to 2025). "In conclusion, HOPX, which regulates tumor-suppressive functions in lung cancer, was found to be associated with image features in this study." (PMID 37190150, 2023). "In lung cancer, HOPX activates Ras and MAPK pathway to cause senescence." (PMID 31934721, 2020). "Loss of HOPX expression as a result of promoter hypermethylation has clinical significance because in patients with gastric and colorectal cancer, the methylation status has been linked to a worse prognosis and patients with strong HOPX expression in lung cancer have a considerably longer survival." (PMID 35681746, 2022). "In contrast, HOPX knockdown partially recovered the malignant phenotypes of lung cancer cells treated with SGI-1027 or si-DNMT3B." (PMID 41660264, 2025). "High HOPX expression effectively suppressed the proliferation, migration, and invasion of lung cancer cells." (PMID 41660264, 2025). "In conclusion, these findings provide a rationale for targeting DNMT3B-mediated HOPX DNA methylation and identify crucial molecular targets for lung cancer therapy." (PMID 41660264, 2025). "In lung cancer cell lines, HOPX is fully or partially methylated, which results in gene silencing or the down-regulation of its gene expression." (PMID 37190150, 2023). "This study established an imaging biopsy with the radiogenomic signatures that links HOPX expression status and CT images to aid the prediction of HOPX expression status and the prognosis for lung cancer patients." (PMID 37190150, 2023). "For example, HOPX transfection of lung cancer cells resulted in enlarged and flattened morphologies, with positive SA—Gal staining indicating senescence, and stimulated the expression of proteins associated with aging, such as SAHFs and p-H2AX." (PMID 35681746, 2022). "The RAS-ERK-MAPK signaling cascade has been identified to be involved in HOPX-induced senescence in lung cancer cells." (PMID 35681746, 2022). "A critical molecular event in the development of lung cancer is the downregulation of HOPX and overexpression of Mycn, and re-expression of HOPX suppresses lung cancer cell proliferation migration and invasion." (PMID 35681746, 2022). "HOPX has been shown to play roles in cardiac development and has tumor suppressive effects in lung cancers (PMID: 15790958, PMID: 17417779, PMID: 12297045)." (PMID 34354115, 2021). "In contrast to the situation in lung cancer, in gastric cancer, the promoter CpG islands of the HOPX gene were found to be strongly hyper-methylated and HOPX gene expression was silenced differently from lung cancer 37,41." (PMID 25154973, 2015). "Moreover, GATA6, in synergy with HOPX, regulated overlapping alveolar differentiation and the expression of aggressive target genes, collectively limiting the metastatic potential of lung cancer cells." (PMID 38483616, 2024). "As a specific transcriptional regulator of differentiation, the low expression of HOPX may result in poorly differentiated tumors and a poor prognosis for patients diagnosed with lung cancer." (PMID 37190150, 2023). "We hypothesized that the reason for this phenomenon was related to the biological functions of HOPX in the lungs and lung cancer." (PMID 37190150, 2023). "Therefore, predicting HOPX gene expression status before treatment will play a vital role in predicting the overall survival of patients diagnosed with lung cancer for the decision-making process regarding personalized treatment plans." (PMID 37190150, 2023). "By tracing the signaling pathway of HOPX, researchers discovered that it has a significant influence on inhibiting lung cancer cell proliferation and suppressing tumor cell migration and invasion, which results in a lower expression in NSCLC and a poor prognosis for patients." (PMID 37190150, 2023). "HOPX promoter methylation has been detected in human uterine endometrial cancer, head and neck cancer, gastric cancer, colorectal cancer, pancreatic cancer, and lung cancer." (PMID 35681746, 2022).
lung carcinoma (continued). "Furthermore, hypermethylation of HOPX DNA is related to gene silencing in lung cancer, where HOPX induces cellular senescence via activation of Ras/MAPK signaling and inhibition of the Akt pathway." (PMID 31934721, 2020). "NKX2.1 induces the expression of HOP homeobox (HOPX) in lung cancer." (PMID 25154973, 2015). "Furthermore, a link between human HOPX and lung cancer has also been proposed, based on the observation that this gene was significantly down-regulated in primary lung tumours compared to normal lung tissue samples." (PMID 19200380, 2009). "Some genes with hypermethylated promoters have been reported in lung cancer, such as GAS7, AQP10, HLF, and HOPX." (PMID 30867848, 2019). "Recent reports studying other cancers demonstrated the mechanism of augmented cancer invasion in HOPX knockdown cells; for example, HOPX knockdown is involved in marked phosphorylation of FAK (focal adhesion kinase) and integrin α5 in human lung cancer." (PMID 24287901, 2013). "More direct evidence for a tumor suppressor role for HOPX has come from in vivo studies, where ectopic expression of HOPX in choriocarcinoma, esophageal, glioblastoma, HEC, gastric, colorectal, and lung cancer cells resulted in decreased tumor growth suppression in vivo." (PMID 35681746, 2022). "However, while HOPX expression is activated by NKX2-1 in lung cancer cells, it was not regulated by NKX2-1 in SU-DHL-5 cells." (PMID 23637834, 2013).
gastric cancer (9 papers, 2012 to 2026). A primary or metastatic malignant neoplasm involving the stomach. "HOPX has been shown to have tumor suppressive effects in several cancers including nasopharyngeal carcinoma and gastric cancer where promoter methylation was associated with tumor stage." (PMID 41280003, 2025). "Gut microbial butyrate enhanced CD8+ T cell cytotoxicity via GPR109A/HOPX, thus, inhibiting gastric cancer carcinogenesis." (PMID 40292459, 2025). "Methylation of the HOPX promoter can occur as an early event in carcinogenesis because it has been detected in the early stages of gastric cancer." (PMID 35681746, 2022). "Similarly, in gastric cancer and breast cancer, HOPX inhibits cell proliferation, colony formation, and invasion and promotes apoptosis." (PMID 41227363, 2025). "In the present study, epigenetic field cancerization was assessed in non-cancerous sites for cysteine dioxygenase 1 (CDO1), homeodomain-only protein X (HOPX), Reprimo, and E-cadherin, because they were cancer-specific and frequent aberrations in gastric cancer." (PMID 31069006, 2019). "Interestingly, HOPX has been demonstrated to suppress tumorigenesis in soft agar in ESCC and gastric cancer as well as pancreatic cancer, hence anchorage independent growth suppression is the common feature of HOPX expression in human cancers." (PMID 22958219, 2012). "The cut-off TaqMeth values of CDO1, HOPX, and Reprimo obtained from comparison between RGC tumor tissues and the RN were very similar with those primary ones, indicating that pin-point dense methylation event may result in cancer formation of both RGC and primary gastric cancer." (PMID 31069006, 2019).
breast carcinoma (8 papers, 2016 to 2025). "The mechanisms of HOPX inactivation is essentially caused by promoter DNA methylation in endometrial, esophageal, gastric, colorectal, and breast cancer." (PMID 31666923, 2019). "HOPX overexpression causes apoptosis and cell cycle arrest in breast cancer cells, suggesting that it could be utilized as a therapeutic target for breast cancer patients." (PMID 35681746, 2022). "Homeodomain‐only protein homeobox (HOPX) downregulation by epigenetic regulation leads to aggressive breast cancer." (PMID 39233332, 2024). "HOPX is involved in regulating the homeostasis of hematopoietic stem cells and is closely related to the development of tumors such as breast cancer, nasopharyngeal carcinoma, and head and neck squamous cell carcinoma." (PMID 37344870, 2023). "Consistent with our previous study in gastrointestinal cancers and breast cancer, the promoter hypermethylation of HOPX dramatically predicts disease recurrence in patients with PTC." (PMID 31666923, 2019). "Furthermore, in patients with breast cancer, HOPX DNA methylation is significantly related to human epidermal growth factor receptor 2 (HER2) positivity and advanced lymph node metastasis, and it predicts an unfavorable clinical outcome." (PMID 41227363, 2025). "Our study has revealed that NAC dramatically alters epigenetic heterogeneity in breast cancer and induces convergent hypomethylation of stem cell quiescence-associated genes, ALDH1L1, HOPX, WNT5A and SOX9, which can potentially be developed as therapeutic targets or biomarkers for chemoresistance." (PMID 30774927, 2019). "Among them, promoter methylation of HOPX is observed very frequently in a cancer-specific manner, and is correlated with worse long-term prognosis in esophageal squamous cell carcinoma, gastric cancer, colorectal cancer, pancreas cancer, and breast cancer." (PMID 31666923, 2019). "CK-5 and P63 were picked because they are both markers of squamous cell carcinoma, and SFTPC, SCGB1A1, and HOPX are markers of LUAD, while CDH1 was picked because SLFN12 has been demonstrated to modulate CDH1 expression in prostate and breast cancers." (PMID 32987632, 2020).
colorectal cancer (7 papers, 2013 to 2026). A primary or metastatic malignant neoplasm that affects the colon or rectum. "In addition, co-expressed gene profiles indicate that HOPX may suppress dedifferentiation of cancer cell in consistent with our previous study on colorectal cancer in which epigenetic silencing of HOPX was associated with poor differentiation." (PMID 31666923, 2019). "Using colorectal cancer organoids, Dmitrieva-Posocco O demonstrated that β-hydroxybutyrate (BHB) increased HOPX expression and inhibited the growth of patient-derived colorectal cancer organoids." (PMID 37537666, 2023). "DNA microarray analysis in colorectal cancer cells showed that the re-expression of HOPX upregulates WTAP and PRDX2 while downregulating genes associated with proliferation, angiogenesis, and invasion both in vitro and in vivo." (PMID 35681746, 2022). "However, in colorectal carcinoma, HOPX was found to be highly expressed in normal stromal cells from the mucosa in comparison with desmoplastic tumor stromal cells within the TME." (PMID 41227363, 2025). "Indeed, poor differentiated histology is significantly associated with HOPX silencing by its promoter methylation in colorectal cancer, and HOPX represents +4 quiescent intestinal stem cells which can interconvert between Lgr5+ active stem cells." (PMID 31666923, 2019). "Here, we review the current understanding of HOPX in the progression of colorectal cancer (CRC)." (PMID 24287901, 2013).
nasopharyngeal carcinoma (7 papers, 2015 to 2025). A carcinoma arising from the nasopharyngeal epithelium. "HOPX hypermethylation promotes metastasis in nasopharyngeal cancer by increasing SNAIL transcription, which facilitates epithelial to mesenchymal transition." (PMID 35681746, 2022). "In nasopharyngeal carcinoma, for example, HOPX has high methylation levels in cancerous tissues, and patients with HOPX hypermethylation have a poor prognosis." (PMID 35860629, 2022). "Here the authors, by analysing methylation profiles, identify HOPX as a suppressor of metastasis in nasopharyngeal carcinoma: mechanistically HOPX inhibits SNAIL transcription through deacetylation-mediated silencing." (PMID 28146149, 2017). "HOPX expression has been reported to be reduced at both the DNA and protein levels of oral and nasopharyngeal cancer cells, and its re-expression promoted cell proliferation and invasion and made the cells more susceptible to UV and cisplatin-induced cell death." (PMID 35681746, 2022). "The HOPX and THY1 are well-studied TSGs in colorectal, ovarian and nasopharyngeal cancers." (PMID 25706888, 2015). "In nasopharyngeal carcinoma (NPC) and hepatocellular carcinoma (HCC) cells, HOPX overexpression inhibits tumor cell migration, invasion, and metastasis via targeting the SNAIL transcription factor." (PMID 41227363, 2025).
cardiac hypertrophy (6 papers, 2013 to 2024). "HOPX is down-regulated in human heart failure, and ablation of HOPX causes cardiac hypertrophy in mice." (PMID 26866591, 2016). "Ablation of HOPX is sufficient to induce an up-regulation of some SRF target genes, and can lead to cardiac hypertrophy in mice." (PMID 23437181, 2013). "HOPX may play a critical role in ARV-induced epigenetic modification, as well as cardiac hypertrophy, through interacting and modulating the function of HDAC." (PMID 34943964, 2021). "In addition to HOPX, we also observed an abrupt elevation in the expression of natriuretic peptide B (NPPB), a gene related to cardiac hypertrophy in adult heart, at an early stage of CM differentiation (T09), which dropped quickly thereafter." (PMID 31722692, 2019).
glioma (6 papers, 2020 to 2025). A benign or malignant brain and spinal cord tumor that arises from glial cells (astrocytes, oligodendrocytes, ependymal cells). "HOPX also label cortical astrocytes and HOPX‐expressing neural stem cells in postnatal mouse brain are biased to generate astrocytes, establishing HOPX as a marker of the astroglial lineage and possible player in gliomas." (PMID 36794762, 2023). "GCL_TI specifically upregulates RG markers TNC, HOPX, PTPRZ1, and VIM, astrocyte markers CLU, LGALS1, as well as genes involved in migration and glioma network formation such as CD44, SPARC, and GAP43 (One peak)." (PMID 36823172, 2023). "In overall survival, low expression HOPX predicted good survival in AML, brain lower grade glioma, cervical squamous cell carcinoma and endocervical adenocarcinoma, colon adenocarcinoma, LUAD, lung squamous cell carcinoma, and STAD." (PMID 31934721, 2020).
lung adenocarcinoma (6 papers, 2015 to 2023). A carcinoma that arises from the lung and is characterized by the presence of malignant glandular epithelial cells. "SGB1A1, SFTPC, and HOPX are all correlated with better survival in lung adenocarcinoma, while our results showed a reduction in mRNA of such markers in most of the cells." (PMID 32987632, 2020). "Furthermore, the alveolar lineage transcription factors, GATA6 and HOPX, were reported to be essential in airway epithelial specification and lung adenocarcinoma subtype metastasis inhibition." (PMID 35681746, 2022). "In H2228 lung adenocarcinoma cells, however, HOPX did not cause senescence, showing that it is involved in oxidative stress and DNA damage-induced cellular senescence but does not cause senescence on its own." (PMID 35681746, 2022). "In the lung, HOPX expression inhibited lung adenocarcinoma formation and metastasis." (PMID 30154568, 2018). "In lung adenocarcinomas, GATA6 and HOPX play critical roles in a lineage-selective pathway to suppress metastasis." (PMID 28146149, 2017). "HOPX is also involved in part of a transcriptional program that is related to distal airway epithelial differentiation and lung adenocarcinoma (LUAD) progression, in which HOPX is considered to induce cellular senescence with the activation of Ras/MAPK signaling and inhibition of the Akt pathway." (PMID 37190150, 2023). "However, HOPX expression has been reported to be elevated in a small number of esophageal carcinoma cell lines (TE2, TE5, KYSE410, and KYSE520), lung adenocarcinoma, and pancreatic cancer Langerhans islet cells." (PMID 35681746, 2022).
glioblastoma (5 papers, 2008 to 2025). The most malignant astrocytic tumor (WHO grade IV). "HOPX has been described as a marker of oRGs and possible actor in glioblastomas." (PMID 36794762, 2023). "In line with this, HOPX has recently been identified as one of the regulators of differentiation and proliferation states in diffusely invading glioblastoma multiforme (GBM) cells." (PMID 41227363, 2025). "HOPX has been proposed to be part of a gene panel characterizing bipotent fetal glial progenitor cells with unspecific localization in telencephalon and similar glioblastoma (GBM) cells." (PMID 36794762, 2023). "There are multiple layers of steps in glioblastoma oncogenesis including the failure of cell fate specific genes (such as p300, BMP, HOPX, NRSF/REST, and others) to keep the cells differentiated in their specific cell type." (PMID 35538578, 2022). "There are multiple layers of steps in glioblastoma oncogenesis including the failure of cell fate-specific genes to keep the cells differentiated in their specific cell types such as p300, BMP, HOPX, and NRSF/REST." (PMID 35538578, 2022). "This study identifies key gliogenic genes having the ability to control oncogenesis in glioblastoma cells, including p300, BMP, PAX6, HOPX, NRSF/REST, LIF, and TGF beta." (PMID 35538578, 2022). "This study identifies key gliogenic genes/signaling pathways having the ability to control oncogenesis in glioblastoma cells including p300, BMP, PAX6 (anti-GBM override), HOPX (tumor suppressive + differentiation), NRSF/REST (astrcytogenic but capable of playing oncogenic role), LIF, and TGF beta." (PMID 35538578, 2022). "Key gliogenic genes having the ability to control oncogenesis in glioblastoma cells: p300, BMP, PAX6, HOPX, NRSF/REST, LIF, and TGF beta.TGF beta: It has a very important gliogenic effect." (PMID 35538578, 2022).